MIR4650-2 (microRNA 4650-2)
Synonyms: hsa-mir-4650-2
Gene: MicroRNA gene on chromosome 7 (72,697,903 to 72,697,978, forward strand). Ensembl gene ENSG00000264494.
Homologues: Paralogues in human: MIR4650-1 (100% identical).